IL4 (interleukin 4)
Diseases named in the same sentence as IL4 in open-access papers (continued):
Sharing a sentence is not in itself a finding about the gene and the disease.
tumor (continued). "We found that the SAA signaling significantly influenced the releasing of many TH1 / TH2 polarization and anti-tumor immunity related cytokines including IFN-α, IL-1β, IFN-γ, IL-4 and etc.." (PMID 37925492, 2023). "The level of IL-1β, IL-6 and TNF-α were increased in tumor mice after DSF treatment, while the level of IL-4, IL-10 and TGF-β were increased after DSF treatment." (PMID 37305383, 2023). "The regulation of ARG1 expression in MDSCs by IL-4, HIF-1α, and STAT3 is well established; however, the factors which regulate ARG2 in tumour cells have received less attention to date." (PMID 35962843, 2023). "The accumulation of TAMs following interactions with CAFs can exhaust the anti-tumor function of NK and CD8 + T cells by secreting TGF-β, COX-2, PGE2, IL-10, IL-4, IL-13, and some others." (PMID 37221555, 2023). "After two vaccinations, APE/OVA induced both IFN-γ-secreting T cells (Th1) and IL-4-secreting T cells (Th2), generating effector CD8+ T cells against tumor growth." (PMID 37514985, 2023). "If the monocytes were to differentiate into interleukin 4 (IL4), IL10/transforming growth factor beta 1 (TGFβ1) activated cells, it would trigger a regenerative response that would amplify the tumor growth." (PMID 38009543, 2023). "In the transwell migration assay, IL-4-treated macrophages performed an enhanced invasive capacity for CT26 tumor cells, indicating that M2 macrophages promoted tumor mobility." (PMID 37446401, 2023). "In contrast, the production of immune checkpoint molecules like PD-1 and the cytokines IL-4 and IL-13 dampens ILC2 activity and accelerates tumor growth." (PMID 37510993, 2023). "The presence of anti-inflammatory cytokines such as IL-4, IL-10, colony-stimulating factor (CSF), and TGF-β promotes the differentiation of recruited Mø into TAMs, which, in turn, enhance tumor cell growth." (PMID 38258072, 2023). "The expression pattern of surface markers in M2 macrophages is heavily influenced by the presence of IL-4, -10, and -13 or MMPs such as MMP-1, MMP-3, MMP-10, and MMP-14, which are secreted by the tumor." (PMID 38033495, 2023). "In the context of cancer, the type 2 cytokines IL-4, IL-5, IL-9, and IL-13 along with ILC2s, Th2, and Th9 cells may either promote or inhibit tumorigenesis in a context-dependent manner that involves complex interactions with cancer cells and the constituents of the tumour microenvironment." (PMID 37455828, 2023). "As Th2 cytokines, IL4 and IL13 have been reported to restrain the immune response to tumor cells and promote the proliferation of KRAS-mutant cells." (PMID 36975441, 2023). "During tumor progression, Th2 cells are recruited to the TME by CCR3 ligands (CCL26, CCL11, and so on), and produce IL-4 and IL-10, which induce M2 polarization of macrophages." (PMID 37063892, 2023). "Mast cells through releasing IL-1, IL-4, IL-6, and TNF-α can actively participate in the elimination of tumor cells and rejection of tumors." (PMID 36793597, 2023). "CLL tumour cells receive supportive microenvironmental signals, such as BCR ligation, IL-4 and CD40L, within the lymph nodes of patients, promoting tumour cell survival, proliferation and drug resistance." (PMID 37528310, 2023). "Increased cholesterol efflux promotes IL-4-mediated reprogramming, including the inhibition of IFN-γ-induced gene expression, which reverts the tumour-promoting functions of TAMs and reduces tumour progression." (PMID 37491279, 2023). "In cervical cancer patients, tumor cells promote the acquisition of a Tc2 cell phenotype by tumor-infiltrating CD8 T cells, which leads to increased production of IL-4 and decreased production of IFN-γ, facilitating immune escape of tumor cells." (PMID 37907738, 2023). "Early establishment of an IgE response via IL-4 toward carcinogenic DNA-damaging environmental xenobiotic 9,10-dimethylbenz-A-anthracene (DMBA) restricts tumor growth in a basophile FC epsilon receptor (FcεRIα)-dependent manner." (PMID 37429945, 2023).
tumor (continued). "As a result of CSCs secreting TGF- and IL-4, CSCs become anti-apoptotic and CD8+ T cell-mediated anti-tumor immune responses are impaired." (PMID 37957420, 2023). "The secretion of immunosuppressive cytokines such as IL-10, IL-4, and TGF-β by B cells and Tregs, in addition to those produced by tumor cells, allows them to escape immune surveillance and leads to subsequent tumor progression and metastasis." (PMID 38139154, 2023). "Activated macrophages are classified into anti-tumor M1 and pro-tumor M2 types by the action of cytokines such as TGF-β1, IL-4, and IL-13." (PMID 37161430, 2023). "IL-4 and IL-13 are produced by several cell types including eosinophils, basophils, mast cells, NKT cells, ILC2 cells, macrophages, Th2 cells, and tumor cells." (PMID 37108657, 2023). "Functionally, neoadjuvant chemotherapy induces proinflammatory cytokines and decreases pro-tumor cytokines from tumor-infiltrating T cells, with enhanced TNF-α and IL-2 and reduced IL-4 and IL-10 expression." (PMID 37173915, 2023). "IL-4 increases the expression of androgens, activates the JNK pathway, and promotes tumour progression." (PMID 38137361, 2023). "Sparse tumor GNPs transdifferentiate into TuAstrocytes, which secrete IL-4 to polarize microglia and induce IGF1 secretion, which is critical for tumor progression." (PMID 37705736, 2023). "Based on the secretion of IL-4, TIME enhanced the immune suppressive M2 which in turn enables tumor growth and progression." (PMID 38095640, 2023). "Together with the impact on IL4-signalling via the JAK1/STAT6 axis, our data strongly support an early tumor suppressive role of miR-494-5p in CRC." (PMID 38201452, 2023). "PAR1CAR-T cells secrete proinflammatory cytokines and chemokines, including TNF-α, IFN-γ, IL-1α, IL-4, IL-6, IL-17A, and GRO, upon encountering PAR1 antigens that exhibit potent cytolytic capacities against PAR1-expressing tumor cells." (PMID 37667257, 2023). "Z. multiflora essential oil (500 mg/kg) reduced tumour weight and balanced T helper 1 levels by increasing the secretion of TNF‐α, Interferon‐gamma (IFN‐γ) and IL‐2 and decreasing IL‐4 levels." (PMID 37697969, 2023). "The release of IL-4 and TGF-β by M2 macrophages inhibit the growth of NK cells and T cells, thus resulting in reduced anti-tumor immunity in the host and insensitivity to chemotherapeutic treatments." (PMID 37647290, 2023). "These cells and tumor cells drive the production of tumor facilitating cytokines such as TGF-β, IL-10, and IL-4, which also promote T-cell and CAR T-cell exhaustion." (PMID 36761757, 2023). "In co-cultures with CD1d+ tumor cell lines, the CD1d-Vδ2 bsTCE triggered type 1 NKT cells to secrete Th1 and Th2-type cytokines, including IL-2, IL-4, tumor necrosis factor (TNF), and interferon (IFN)-γ, whereas Vγ9Vδ2-T cells mainly secreted TNF and IFN-γ." (PMID 36868236, 2023). "We next determined the effect of Q11 on the secretion of tumor‐promoting inflammatory cytokine, and found that the TGF‐β level in the conditioned medium was significantly increased in the IL‐4/IL‐13 induced group but decreased upon Q11 treatment." (PMID 37875398, 2023). "NKT cells are activated by the specific glycolipid antigen α-galactosylceramide (α-GalCer) and proliferate and differentiate into two directions, IFN-γ-producing and IL-4-producing NKT cells, with the former anti-tumor and the latter pro-tumor." (PMID 37833255, 2023). "We show that administration of naive CD4+ T cells polarized to Th2 cells, using IL-4, IL-2 and anti-IFN-γ antibody, not only prevented tumor growth, but reversed growth curve of colon and pancreas cell-derived allograft tumors." (PMID 36376448, 2023). "After secretion of anti-inflammatory cytokines by M1 TAMs at the site of injury, M2 TAMs can be recruited to the primary tumor site, where type 2 ILC and TH2 reaction products such as interleukin (IL)-4 and IL-13 are present." (PMID 37004014, 2023).
tumor (continued). "IL-4 and IL-10 levels decreased more in the combination treatment than doxorubicin or PFPE alone, which correlated with reduced tumor progression." (PMID 37238871, 2023). "In the present study, compared to those of pro-inflammatory cytokines, the levels of anti-inflammatory cytokines including IL-4, IL-10 and tumor growth factor-β (TGF-β) were suppressed in tumor-bearing mice after DSF treatment." (PMID 37305383, 2023). "Another application of ALDH expression in melanoma CSCs is the development of a dendritic cells (DCs) vaccine (CSC-DC vaccines) which stimulates tumour infiltration with T cells, along with their products (INF-γ and IL-4)." (PMID 35334544, 2022). "Monocytes from PBMCs were cultured in a medium with GM-CSF and IL-4; pulsed with Keyhole Limpet Hemocyanin (KLH) and autologous tumor cell lysate in the presence of GM-CSF and TNFα." (PMID 36011029, 2022). "A previous study reports that administering Her2/neu DNA vaccination to HSP90B1 HER2+ breast cancer-carrying mice improved immune response against tumours, which was indicated by higher IFN-/IL-4 levels and reduced Tregs at the tumour site." (PMID 36291587, 2022). "Some examples are reported in several studies that have demonstrated the release of chemokines and cytokines such as CCL21; IL-2; IL-4; IL-18; IL-24; IFN-γ; and LIGHT, also known as a lymphotoxin analogue, into the tumor microenvironment." (PMID 36077761, 2022). "Given this successful improvement of the stimulatory capacity of IL4 DCs, we subsequently showed that combining in situ downregulation of PD-L1 and PD-L2 with introduction of interleukin-15 transpresentation tools could further potentiate tumor-reactive T-cell expansion." (PMID 35250967, 2022). "During the GBM process, hyperactivity of HDAC3, 5, and 9 is expressed in IL-4-induced M2 GAMs that increase the levels of TGFβ and IL-10, resulting in exacerbating the immunosuppressive capacity of GBM tumor cells." (PMID 35572545, 2022). "The expression of VISTA on CD4+ T cells in tumor tissue showed low secretion of cytokines including IFN-γ, IL-2, IL-4, IL-10, IL-17, and IL-12p70." (PMID 35122478, 2022). "After the injection of these liposomal nanoformulations into a TUBO breast tumor murine model, increased IL-4 and IFN-γ secretion, reduced tumor size and prolonged survival time in therapeutic and prophylactic models were observed." (PMID 35335881, 2022). "In an IgE-dependent skin allergic inflammation model similar to IgE-CAI, basophil-derived IL-4 promotes the expression of adhesion molecules, resulting in the enhanced recruitment of eosinophils." (PMID 35693800, 2022). "In contrast, the cytokines IL-10, IL-4 and TGF-β from Th2 cells were proven to promote tumor cell dissemination and metastasis in various cancers." (PMID 35688915, 2022). "Th2-driven inflammation can be typically found at tumor sites and tumor microenvironment (TME), and evidence demonstrates that IL-4 boosts tissue-resident macrophage proliferation." (PMID 36305904, 2022). "IL4 signaling in macrophages upregulates the expression of the chemokine receptor CXCR2, necessary for IL4-mediated tumor cell extravasation in vitro." (PMID 36077870, 2022). "The effects of yeast and Lactobacillus for either treatment or vaccination (3 times/week) on the tissue and serum levels of TGF-β, IL-4, IL-10, and IFN-γ were measured on day 35 of tumor cell transplantation." (PMID 35974992, 2022). "The peri-tumoral administration of flagellin significantly inhibits tumor growth by increasing the levels of IFN-γ and IL-4." (PMID 36077761, 2022). "CSCs can recruit immunosuppressive properties of DCs by producing immunosuppressive cytokines, including IL-13, IL-10, IL-4, and co-inhibitory molecules like B7-H3, IDO1 and PD-L1 which induce tumor properties of DCs." (PMID 36207500, 2022). "In spleen cell supernatants, IFN-γ, IL-4, IL-1β, IL-6, IL-13, MCP-1, and IL-21 were significantly higher in the tumour-bearing SID animals compared to the healthy controls." (PMID 36010845, 2022).
tumor (continued). "Nevertheless, is well-known that MCs through releasing IL-1, IL-4, IL-6, IL-8, TNF-α, IFN-γ, TGF-β, MCP-3, MCP-4, leukotriene B4 (LTB4) and chymase can contribute to inflammation, inhibition of tumour cell growth, and induction of tumour cell apoptosis." (PMID 35406451, 2022). "Consistently, in those B16F10 tumor-bearing Jα18-/- chimeric mice, α-GC induced less IFN-γ and IL-4 production in intratumoral CD45.2+Vdac1+/- iNKT cells, despite their normal granzyme B production." (PMID 36741382, 2022). "The frequencies of CD4+IL-4+, CD4+IL-17+ and CD8+IL-10+ showed significant increases in laryngeal SCC patients with tumor size ≤ 3 cm (P = 0.024, P = 0.048, P = 0.001, respectively)." (PMID 36376825, 2022). "As regulated by the primary tumor, MDSCs arrived in the metastatic organs before the tumor cells and conditioned it to promote tumor seeding by secreting b-FGF, IGF-1, IL-10, IL-4, IL-1β, SDF-1, and MCP-1." (PMID 35267547, 2022). "Interleukin 4 (IL4) is a cytokine that induces differentiation of T cells and is present in the tumor environment of many cancers." (PMID 35565241, 2022). "Overall, NEO increased the proinflammatory function of tumor-infiltrating CD4+ T cells, with enhanced TNF-α and IL-2 but reduced IL-4 and IL-10 expression." (PMID 36509285, 2022). "Wang reported on the novel IL-4 and IL-21 incorporation of inverted cytokine receptor (ICR), which enhances the efficacy of CAR-T cells in the IL-4 tumor environment." (PMID 36291802, 2022). "On the other hand, cytokines such as IL-4, IL-13, and MYC influence the development of “alternative” M2 macrophages, having pro-tumor activity, with angiogenesis induction." (PMID 36294305, 2022). "By contrast, expression of Il9 and Il4, known cytokine inducers of MMC and CTMC respectively, showed a marked IL-33 dependent increase in gp130F/F antral tumours, with levels in gp130F/FIl33−/−compound mutants comparable to those of WT controls." (PMID 35677533, 2022). "IL-4 and IL-13 have both been shown to supress the anti-tumoural immune response, and moreover to directly drive the proliferation of KRAS-mutant tumour cells." (PMID 36010845, 2022). "M2 TAMs secrete pro-tumor factors (such as IL-4, IL-6, IL-10, IL-13, EGF, and VEGF), while the tumor suppressor M1 TAMs expresses anti-tumor factors (such as IL-12, the major histocompatibility complex (MHC) class II, and TNF-α)." (PMID 36358823, 2022). "On the contrary, they also release various cytokines, such as INF-γ, after being activated by tumor antigens, preventing macrophages from migrating away from the tumor antigens, as well as TNF-ɑ, IL-4, and IL-5." (PMID 36611336, 2022). "In summary, CSCs release a variety of immunosuppressive cytokines and chemotactic factors such as; PGE2, IL-10, TGF-β, IL-4, IL-13 and IL-35 that affect different immune cells in the TME and promote tumor invasion and progression." (PMID 36207500, 2022). "IL-4 is mainly produced by type II helper T (Th2) cells, which enhances tumor growth, metastatic and invasive ability of CRC cells, tumor metabolism, and the growth of metastatic tumors." (PMID 35953863, 2022). "The PD-1/CD28 CSR reverses inhibitory signals transmitted by tumor cells, whereas the IL-4/7 ICR reverses inhibitory effects of IL-4." (PMID 35392217, 2022). "IL-2, IL-9 and IL-15 show tumor-suppressive effects in CRC, while IL-4 and IL-7 exert pro-tumorigenic effects." (PMID 36611932, 2022). "It has been revealed that in the microenvironment of HNSCC, increased expressions of IL-4, IL-10 and transforming growth factor β (TGF-β) suppress adaptive immunity and promote tumor escape from immune system." (PMID 36376825, 2022). "And IL-33 can stimulate the production of cytokines (IL-4, IL-6) and chemokines (CCL2, CCL3, CCL7, CXCL1), which are also involved in the construction of the tumor microenvironment." (PMID 36110250, 2022).
tumor (continued). "T lymphocytes mediate tumor immunity by secreting various cytokines into the TME, such as IL-2, IL-4, IL-5, IL17, IL-21, IL-22, and IFN-γ." (PMID 35464411, 2022). "IL-4, the predominant cytokine produced by TFH, was shown to trigger production of CXCL12 by FRC-like stromal cells, thus supporting FL tumor cell activation and survival." (PMID 33842331, 2021). "Of the cytokines analysed, nine (CD30L, CCL11, CCL24, IGFBP5, IL-4, IL-13, MIP-3ß, CXCL4 and TPO) were significantly more abundant in 4T1 primary tumours than in 67NR primary tumours (Fig. 4aiii)." (PMID 33795809, 2021). "Due to the relatively low number of tumor cells in early CRC stages as well as ILC2 cells, the Th2 cells seem to be the main source of IL-4 in the II and III stages." (PMID 35008550, 2021). "Densitometry analysis showed that five cytokines, IL-4, AXL, IL-1β, IL-9, Exotaxine-2 and IL2, were upregulated, and two cytokines, PF4 and IL-6, were downregulated in the tumor environment of JEG3-Sh-NLRP7 cells." (PMID 34203890, 2021). "Neutrophils which exist in tumor microenvironment are capable of producing angiogenic chemokines and cytokines including CCL2,CCL3, CCL5, CCL10, IL4 and IL10 to promote tumor growth, invasion and angiogenesis." (PMID 34123808, 2021). "It was shown, that circulating monocytes or tissue residing macrophages are recruited and stimulated by different tumor-derived signals, such as chemo-attractants, e.g. CCL2 or cytokines, e.g. IL-4, IL-10 and IL-13." (PMID 34579743, 2021). "These tumor-infiltrating TAM are skewed toward CD163+ M2 phenotype under the action of the transcription factor, GATA3, and cytokines, including IL-4, IL-6, and IL-13, and promoted an immunosuppressive TME in EAC." (PMID 33995371, 2021). "Ablation of XBP1 inhibited the expression of the pro-tumor cytokine signature of TAMs, including IL-6, VEGFA, and IL-4." (PMID 34667145, 2021). "Macrophages can be polarized into M1 macrophages, which have anti-tumor functions induced by IFN-γ alone or with lipopolysaccharides and M2 macrophages, which exhibit pro-tumor function induced by IL-4 and IL-1320." (PMID 34591416, 2021). "On the contrary, M2 cells are activated by type II cytokines such as IL-4, IL-10, IL-13, and transforming growth factor (TGF)-β, performing a pro-tumor immune response by producing factors as STAT3, which contribute to tumor proliferation." (PMID 33917013, 2021). "Taken together, these results demonstrated that both IL-4 and IL-13 were upregulated in ILC2s of NSCLC patients, particularly in ILC2s derived from tumor tissues." (PMID 34194433, 2021). "Higher expression levels of IL-4 and IL-13 were found in the serum or the tumor homogenates of a CT26 tumor-bearing mouse model." (PMID 33450900, 2021). "Results demonstrated a significant reduction in tumor size and the highest levels of IFN-γ and IL-17 and the lowest levels of IL-4 FoxP3, HIF-1α, VEGF, MMP-2, and MMP-9 in the IT+IP+TEX-treated group." (PMID 34194604, 2021). "MSCs can promote tumor growth by dwindling the IFN-γ release from TH1 and increasing IL-4 expression from TH2." (PMID 33933086, 2021). "IL4 and IL13 were highly expressed in ILC2s obtained from tumor tissues (IL4, P<0.0001; IL13, P<0.0001) and PBMCs (IL4, P<0.0001; IL13, P<0.0001) obtained from NSCLC patients than those obtained from HDs." (PMID 34194433, 2021). "In the present experiments, we showed that increased production of IL-4 induced a decrease in CXCL17, leading to suppression of tumor formation by blocking the recruitment of MDSCs into the tumor microenvironment." (PMID 33670758, 2021). "Overall, we observed a significant increase in IL-4 and TOX expression in the tumor stage, with a positive correlation between the levels of TOX and IL-4 expression." (PMID 34220814, 2021).